NF1 (neurofibromin 1)
Diseases named in the same sentence as NF1 in open-access papers (continued):
Sharing a sentence is not in itself a finding about the gene and the disease.
neurofibromatosis type 1 (continued). "Neurofibromatosis-type 1 (NF1) was diagnosed in a 29-year-old lady with wild type (c-kit/PDGFR negative and SDH retained) gastric GIST having café-au lait spots with her son also reporting similar macular skin lesions." (PMID 36816783, 2023). "We previously discovered a sex-by-genotype defect in microglia function using a heterozygous germline knockout mouse model of Neurofibromatosis type 1 (Nf1 ± mice), in which only microglia from male Nf1 ± mice exhibited defects in purinergic signaling." (PMID 36890585, 2023). "NF1 (Online Mendelian Inheritance in Man database number 162200), also referred to as Von Recklinghausen disease, is an inherited syndrome that favors the development of tumors and other clinical manifestations." (PMID 37627552, 2023). "Here, we present the case of a young female carrying pathogenic NF1 and COMP mutations, diagnosed with two distinct heritable disorders, neurofibromatosis type 1 and pseudoachondroplasia." (PMID 36890482, 2023). "Malignant PNST in humans often develops subsequent to neurofibromatosis type I in which inactivation of the NF1 tumor suppressor gene (TSG) results in activation of the MAP kinase signaling pathway." (PMID 37369741, 2023). "The neurofibromatosis disease spectrum includes neurofibromatosis types 1 and 2 (NF1, NF2) and schwannomatosis (SWN)." (PMID 37301968, 2023). "The most frequently used author keywords (DE) were: “malignant peripheral nerve sheath tumor”, “MPNST”, “neurofibromatosis type 1”, “sarcoma”, “nf1”, “schwannoma”, “immunohistochemistry”, “chemotherapy”, “MRI”, and “radiotherapy”." (PMID 36776342, 2023). "A woman with neurofibromatosis type 1 (NF-1) treated with chemotherapy and radiation at < 6 years of age due to left-sided optic glioma." (PMID 37326844, 2023). "The diffuse form of GNs is strongly associated with multiple syndromes, including Neurofibromatosis 1 (NF1), also known as von Recklinghausen’s disease, Multiple Endocrine Neoplasia type 2B (MEN2B), and Cowden Syndrome." (PMID 37218882, 2023). "Neurofibromatosis type I (NF1) microdeletion syndrome, accounting for 5–11% of NF1 patients, is caused by the heterozygous deletion of NF1 and a variable number of flanking genes in the 17q11.2 region." (PMID 37145209, 2023). "In many of them, mutations in a single gene can explain most cases, e.g., PAX6 and aniridia ⁠, ABCA4 and Stargardt disease ⁠, or NF1 and Neurofibromatosis type 1 ⁠." (PMID 36881176, 2023). "NFNS1 is estimated to have a higher frequency than 25% of neurofibromatosis 1 patients because of being misdiagnosed as classic NF1 or NS." (PMID 36803953, 2023). "Radiographic partial response (PR) or sustained stable disease (SD) was observed in 5 patients treated with trametinib monotherapy among which, 4 had neurofibromatosis type 1; one patient with NF1 mutant sporadic glioma had SD followed by disease progression." (PMID 38143440, 2023). "To date, three neurofibromatosis have been described: neurofibromatosis type 1 (NF1, or von Recklinghausen disease), neurofibromatosis type 2 (NF2), and schwannomatosis (NF3)." (PMID 36899941, 2023). "The two most common forms are NF1 (peripheral neurofibromatosis, also known as Recklinghausen’s disease), followed by NF2 (central neurofibromatosis)." (PMID 35204451, 2022). "Optic pathway gliomas are often asymptomatic tumors occurring in children with neurofibromatosis type 1 (NF1 + OPG) or sporadically (spOPG)." (PMID 34994964, 2022). "Neurofibromatosis type 1 (NF1, OMIM #162200), formerly known as von Recklinghausen’s disease, is a complex tumor predisposition syndrome, inherited in autosomal dominant pattern with an estimated incidence of 1:2500–3000 live births." (PMID 35885913, 2022). "There are several familial disorders associated with adrenal pheochromocytoma, the most common are: von Hippel-Lindau syndrome (VHL), multiple endocrine neoplasia type 2 (MEN2) and neurofibromatosis type 1 (NF1)." (PMID 36523722, 2022).
neurofibromatosis type 1 (continued). "The frequently observed molecular diagnoses (observed in more than one patient) include Osteogenesis Imperfecta Type I (COL1A1, MIM:166200), Neurofibromatosis, Type I (NF1, MIM:162200) and Marfan Syndrome (FBN1, MIM:154700)." (PMID 35346302, 2022). "Multiple endocrine neoplasia type 1 (MEN1), von Hippel–Lindau disease (VHL), neurofibromatosis 1 (NF-1) (von Recklinghausen disease), and the tuberous sclerosis complex (TSC) are pancreatic endocrine tumors (PETs)." (PMID 36077529, 2022). "Variants found in cases of the cancer cohort were in genes: RB1 and NF1, both coherent with the phenotype of the patients: Retinoblastoma and Neurofibromatosis type 1, respectively." (PMID 35087072, 2022). "Neurofibromatosis type 1 (NF1) is a multi-symptom neurogenetic disorder caused by heterozygous loss-of-function mutations in the neurofibromin 1 (NF1) gene, which encodes neurofibromin, a tumor suppressor that inhibits signaling via the small GTPase rat sarcoma virus (RAS) subfamily of proteins." (PMID 36037004, 2022). "Neurofibromatosis type 1 (NF1) is a genetic disease, with autosomal dominant transmission, related to pathogenic variant of the tumor suppressor gene NF1 (17q11.2), predisposing affected subjects to a variety of benign (neurofibromas and plexiform neurofibromas) and malignant tumors." (PMID 36553133, 2022). "An MRS study using Nf1+/- mice, a mouse model of neurofibromatosis type 1, showed increased GABA/Glu ratios in the prefrontal cortex and striatum, but not in the hippocampus." (PMID 35183218, 2022). "An estimated 5–11% of patients with neurofibromatosis type-1 (NF1) harbour large deletions encompassing the NF1 gene and flanking regions." (PMID 34535841, 2021). "Neurofibromatosis type 1 (NF-1), also known as Von Recklinghausen's disease, is an autosomal-dominant disease that is characterized by high-frequency mutations leading to multiple benign tumors called neurofibromas and café au lait spots on the skin." (PMID 34909339, 2021). "NF1 mutation was detected; selumetinib (a MEK inhibitor) is an approved treatment for patients diagnosed with neurofibromatosis type 1 with neurofibroma-related complications." (PMID 34771600, 2021). "These include SDH-deficient GIST mainly affecting pediatric and young adult population, NF1-mutant GIST both sporadic and syndromic (associated with type I neurofibromatosis), RAS-mutant, FGFR mutant GISTs and others." (PMID 33402214, 2021). "Neurofibromatosis type 1 (NF-1) or von Recklinghausen's disease, an autosomal dominant genetic disorder, is characterized by a café au lait spot and cutaneous neurofibromas." (PMID 34090195, 2021). "Neurofibromatosis type 1 (NF-1), also known as von Recklinghausen's disease, is an autosomal dominant multisystem genetic disorder affecting one in 2,600 individuals." (PMID 33907652, 2021). "The majority of PNETs are sporadic, but some are associated with genetic syndromes, such as multiple endocrine neoplasia type 1 (MEN-1), von Hippel-Lindau (VHL) disease, neurofibromatosis type 1 (NF-1), and tuberous sclerosis (TS)." (PMID 32899271, 2020). "Neurofibromin 1 and 2 are involved into the pathogenesis of neurofibromatosis 1, neurofibromatosis 2, and schwannomatosis in humans." (PMID 32552868, 2020). "STS, soft tissue sarcomas; MRT, malignant rhabdoid tumor; CNS, central nervous system; MPNST, malignant peripheral nerve sheath tumor; NF-1, neurofibromatosis type 1; NF-2; neurofibromatosis type 2, GI, gastrointestinal; NA, data not available." (PMID 33796273, 2020).
neurofibromatosis type 1 (continued). "Neurofibromatosis type 1 (NF-1), the incidence of which is 0.33%, is more common than neurofibromatosis type 2 (NF-2); NF-1 are frequently associated with musculoskeletal system defect, especially deformity; the incidence is 10%-64%." (PMID 32461987, 2020). "Neurofibromatosis type 1 (NF1) is a relatively common autosomal dominant disorder which is caused by inherited or sporadic mutations in the NF1 gene." (PMID 32076030, 2020). "Neurofibromatosis type 1 (NF1) is an autosomal dominant disorder showing complex phenotypes and it is caused by inherited mutations in the NF1 gene, which is a tumor suppressor." (PMID 32075265, 2020). "Hereditary pilocytic astrocytoma is often associated with germline genetic alterations in the tumor suppressor NF1, the gene responsible for the syndrome neurofibromatosis type 1." (PMID 32082673, 2020). "Several cancer predisposing syndromes (CPS) associated with an increased risk of developing to pHGG have been identified so far, including Neurofibromatosis type 1 (NF1), Turcot syndrome and Li-Fraumeni syndrome." (PMID 33282797, 2020). "An estimated 5–11% of patients with neurofibromatosis type 1 (NF1) harbour NF1 microdeletions encompassing the NF1 gene and its flanking regions." (PMID 32533297, 2020). "Neurofibromatosis type-1 (NF1), also called von Recklinghausen disease, is a rare autosomal dominant disorder which can be either inherited or sporadic." (PMID 31301733, 2019). "About one in 3,500 people have a genetic disorder called neurofibromatosis type 1, often shortened to NF1, making it one of the most common inherited diseases." (PMID 31545171, 2019). "Ten affected NF1 probands and their available relatives from 10 unrelated Chinese families with neurofibromatosis type 1 were clinically studied." (PMID 31347283, 2019). "Two patients with clinically diagnosed neurofibromatosis type I were referred to our laboratory in order to perform genotyping of NF1 gene." (PMID 31507634, 2019). "Neurofibromatosis type-1 (NF1), also called von Recklinghausen disease, is a rare genetic disease which can lead to the development of benign or even malignant tumors." (PMID 31301733, 2019). "Neurofibromin-1 (NF1) is a RAS-GAP protein whose loss of function induces tumorigenesis in the absence of other alterations in RAS/RAF/ERK pathway, as it happens in neurofibromatosis type I." (PMID 31117237, 2019). "The present study newly revealed that neurofibromatosis type I patients with mutations located in the CSRD and HLR of the NF1 gene had a higher and lower risk than patients with mutations in other regions, respectively, of developing OPG." (PMID 30087692, 2018). "In patients with the disorder Neurofibromatosis type 1, NF1 mutant SCs proliferate and form SC tumors called neurofibromas." (PMID 30470263, 2018). "Although the NF1 sequence has been known for nearly 30 years, the correlation between genotype and phenotype in neurofibromatosis type I remains poorly understood." (PMID 30087692, 2018). "Neurofibromatosis type 1 (NF1) is the most commonly inherited neurological human disorder, affecting about 1 in 3000 people worldwide and is caused by heterozygous mutations of the Nf1 gene." (PMID 28837387, 2018). "Neurofibromatosis Type 1 (NF1) is a genetic disease caused by mutations in Neurofibromin 1 (NF1)." (PMID 30302402, 2018). "For example, haploinsufficiency for the tumor suppressor gene neurofibromin 1 (NF1) is accompanied by increased variation of dendrite formation in neurofibromatosis type 1 patients." (PMID 29242386, 2018). "NF1, also known as von Recklinghausen’s disease, is the most common autosomal dominant single-gene neurodevelopmental disorder, with an incidence of 1:2700." (PMID 30481737, 2018). "For example, the autosomal-dominant syndromes neurofibromatosis type 1 (NF1) and tuberous sclerosis (TS) are caused by inactivating mutations in NF-1 and TSC1/2, respectively." (PMID 29255447, 2017).
neurofibromatosis type 1 (continued). "NF1, PTEN and TCS1/2 mutations have been reported both in familial syndromes, such as type 1 neurofibromatosis, Cowden syndrome, and tuberous sclerosis complex, and in sporadic NETs." (PMID 28042953, 2017). "Plexiform neurofibromas are benign tumors that tend to occur in patients suffering from neurofibromatosis type 1 (NF-1)." (PMID 28634493, 2017). "We present a case of spontaneous renal artery dissection (SRAD) in a 28-year-old female with history of neurofibromatosis type I (NF-1) treated successfully with endovascular stenting." (PMID 27867667, 2016). "Neurofibromatosis type 1 (NF1) is a hereditary disorder caused by mutations in the NF1 gene." (PMID 26962827, 2016). "Neurofibromatosis-Noonan syndrome (NFNS) is a distinct entity which shows the features of both NF1 (neurofibromatosis 1) and Noonan syndrome (NS)." (PMID 26758488, 2016). "There are three major clinically and genetically different forms of neurofibromatosis, neurofibromatosis types 1 and 2 (NF1 and NF2), and schwannomatosis." (PMID 27597922, 2016). "But a mouse in which Nf1 has been turned off in specific organs or tissues other than the heart can survive, and these mice are used to model Neurofibromatosis type I and to help to identify potential treatments." (PMID 26460546, 2015). "Neurofibroma (NF) is a benign tumor of neuronal origin that occurs as a single or multiple lesion associated with neurofibromatosis type 1 (NF1), which is a systemic condition caused by a germline mutation in the NF1 gene, a tumor suppressor gene located at 17q11.2." (PMID 26770842, 2015). "In particular, mutations of VHL, NF1 and RET cause well characterized cancer susceptibility syndrome (von Hippel Lindau, Neurofibromatosis Type 1 and MEN2, respectively)." (PMID 26084817, 2015). "A defect in the NF1 gene on chromosome 17q11.2 leads to NF type 1 or von Recklinghausen’s Disease, first identified in the late 19th century." (PMID 25949273, 2015). "Heterozygous 17q11 microdeletions that encompass NF1 and RNF135 cause a subset of neurofibromatosis type 1." (PMID 24963031, 2014). "Both evidence in patients and studies in the NF1 KO mouse model of neurofibromatosis type 1 point to defects in GABAergic transmission, although with contrasting results." (PMID 24904277, 2014). "Neurofibromatosis type 1 or NF1 is distinct from neurofibromatosis type 2 (NF2), which is less common." (PMID 25026295, 2014). "The GAP activity of Nf1 has profound implications in the pathology and complications of Neurofibromatosis type 1." (PMID 25301738, 2014). "Neurofibromatosis 1 (NF1) (von Recklinghausen disease) is an autosomal dominant inherited disease, characterized by multiple neurofibromas, café-au-lait spots, and other mesenchymal tumors." (PMID 25593916, 2014). "Neurofibromatosis type I (NF-1; formally known as von Recklinghausen disease) is an autosomal dominant disorder associated with learning disabilities and attention deficits, amongst other manifestations." (PMID 25391045, 2014). "Among these the NF1 is also called the peripheral neurofibromatosis, popularly called von Recklinghausen's disease with a reported prevalence of 1 : 5000 in the population and a birth incidence of 1 in 2500–3300." (PMID 25478247, 2014). "Neurofibromatosis type 1 (NF1, von Recklinghausen's disease) is an autosomal-dominant disorder occurring in 1 out of 3,000 births that is caused by the inactivation of the NF1 gene." (PMID 24386562, 2013). "Nf1 is responsible for the genetic disease Neurofibromatosis type I, and recent data strongly suggest that this RasGAP connects different signaling pathways." (PMID 23082153, 2012). "Neurofibromatosis-1 (NF-1), known as von Recklinghausen’s disease, is an autosomal dominant, multisystem disorder that occurs in 1 in 2,500–3,000 live births." (PMID 22824559, 2012). "About 50 % of MPNSTs are known to develop into cases of neurofibromatosis type 1 (von Recklinghausen’s disease, NF-1)." (PMID 22515616, 2012).
neurofibromatosis type 1 (continued). "It belongs to the family of phakomatoses and is subcategorized into two types: NF-1 (von Recklinghausen's disease) and NF-2 (bilateral acoustic neurofibromatosis)." (PMID 21569290, 2011). "Neurofibromatosis type 1 (NF-1), or von Recklinghausen's disease, is an autosomal dominant disorder characterized by cutaneous hyperpigmentation and multiple neurofibromas." (PMID 22018031, 2011). "Neurofibromatosis type 1 (NF-1) is a possible but undocumented idiopathic etiology of occipital neuralgia." (PMID 21569290, 2011). "Neurofibromatosis type-1 (NF-1), also known as von Recklinghausen disease, is an autosomal dominant condition with an approximate incidence of one in 3000 births." (PMID 19568560, 2009). "The study presents the first molecular evidence of inactivation of both copies of the NF1 gene in a typical superficial spreading melanoma of a patient with neurofibromatosis type 1." (PMID 16961930, 2006). "Learning and memory deficits observed in human Neurofibromatosis type 1 patients have been modeled in a Nf1 gene knock-out murine system showing well characterized spatial learning and memory deficiencies." (PMID 16524466, 2006). "We demonstrate that normal tissues in neurofibromatosis type 1 commonly harbor second hits in NF1, the extent and pattern of which may underpin the syndrome’s cancer phenotype." (PMID 40000831, 2025). "Neurofibromatosis type 1 (NF-1) is also known as von Recklinghausen disease." (PMID 40230769, 2025). "A five-year study on prenatal diagnosis (PND) for neurofibromatosis type 1 (NF1) involving 146 women who underwent 205 procedures, primarily chorionic villus biopsies (88%), found the NF1 variant in 85 fetuses (41%), while 122 tested negative (59%)." (PMID 39860457, 2025). "In vitro studies demonstrated that tovorafenib increased ERK phosphorylation at clinically relevant concentrations in cells with neurofibromatosis type 1 loss-of-function (NF–1-LOF), indicating activation rather than inhibition of the MAP kinase pathway." (PMID 40867225, 2025). "We chose to focus on GISTs in Von Recklinghausen disease and to exclude sporadic GISTs with an NF1 mutation but without evidence of the genetic disease, to avoid confusion bias and homogenize our study population." (PMID 40043354, 2025). "The most common form is NF-1, also known as Von Recklinghausen disease." (PMID 40242387, 2025). "NF-1, also known as von Recklinghausen disease, is an autosomal dominant condition resulting from a fundamental defect in neural crest cells, leading to the development of ectodermal and mesodermal derivatives that impact approximately one in every 2,500-3,000 births." (PMID 40230769, 2025). "Neurofibromatosis type 1 (NF1) is the most common RASopathy (diseases involving mutations impacting the RAS/MAPK pathway) with prevalence of 1/2500–1/3000 and is caused by an inherited or de novo mutation in the NF1 gene." (PMID 38339230, 2024). "In addition, in young patients without a RET germline mutation, a careful clinical evaluation with a consideration of germline NF1 gene analysis is ideal to exclude Neurofibromatosis type 1 (NF1)." (PMID 38655100, 2024). "Neurofibromatosis type 1—Neurofibromatosis type 1 (NF1), a.k.a. von Recklinghausen syndrome, is one of the prevalent genetic neurocutaneous disorders caused by the mutation of a tumor suppressor gene, Neurofibromin 1, which inhibits the Ras protein." (PMID 38893137, 2024). "It should be noted that the tumor is either sporadic or, more commonly, may be associated with neurofibromatosis type 1 (NF1), as about 25% to 50% of people with MPNST also have NF1." (PMID 39759655, 2024). "The NF1 germline and somatic variants were observed in a patient without a prior clinical diagnosis of neurofibromatosis type 1, demonstrating that the loss of heterozygosity of NF1 functions as a potential MTC driver." (PMID 38655100, 2024).